MYT1L (myelin transcription factor 1 like)
Diseases named in the same sentence as MYT1L in open-access papers (continued):
Sharing a sentence is not in itself a finding about the gene and the disease.
glioblastoma (4 papers, 2022 to 2025). The most malignant astrocytic tumor (WHO grade IV). "Using the M059J cell line as a model system, we compared the role of MYT1L in DNA-PK-deficient glioblastoma cells and normal DNA-PK cells." (PMID 40362634, 2025). "Conversely, the enforced expression of MYT1L inhibited cell proliferation and induced a G1 cell cycle arrest, suggesting a tumor suppressor role of MYT1L in DNA-PK-deficient glioblastoma cells, although it suppressed apoptosis." (PMID 40362634, 2025). "Quantitative real-time RT-PCR (qRT-PCR) showed that the CXCR1 expression was up-regulated in A-172 and M059K glioblastoma cell lines, which positively correlated with MYT1L protein levels." (PMID 40362634, 2025). "Our previous studies indicated that MYT1L was overexpressed in glioblastoma cell lines and 46.9% of malignant glioma tissue samples (n = 32), functioning as an oncogene in glioblastoma cells with normal DNA-PK activity." (PMID 40362634, 2025). "Our previous studies have uncovered that miR-141 was down-regulated in glioblastoma and was able to suppress cell proliferation by directly targeting MYT1L, implicating an oncogenic role of MYT1L in glioblastoma." (PMID 40362634, 2025). "In this study, we found that in normal DNA-PK glioblastoma M059K cell lines, knockdown of MYT1L attenuated cell proliferation and induced apoptosis and S-phase cell cycle arrest." (PMID 40362634, 2025). "Western blotting revealed that MYT1L was overexpressed in all three glioblastoma cell lines (A-172, M059J, and M059K) and in three of seven neuroblastoma cell lines that were examined." (PMID 40362634, 2025). "It has also been reported that MYT1L was found to be deleted (~5%) and downregulated (>80%) in glioblastomas, suggesting that gliomagenesis requires neutralization of terminal neural differentiation." (PMID 35869058, 2022). "Using a unique glioblastoma cell model system, M059J with deficient DNA-PK, while M059K with normal DNA-PK, we demonstrate in vitro that MYT1L-overexpressing cells show non-oncogene addiction to DNA-PK." (PMID 40362634, 2025). "To see whether MYT1L is also up-regulated in neuroblastoma, we compared its expression in both glioblastoma and neuroblastoma cell lines." (PMID 40362634, 2025). "Although this is the first report regarding the critical role of DNA-PK/MYT1L in the proliferative IL-8/GROα-CXCR1 signaling loop in glioblastoma, the significant contributing role of IL-8-CXCR1/2 axes in the proliferation and angiogenesis of glioblastoma cells has been demonstrated before." (PMID 40362634, 2025). "It was found that MYT1L was overexpressed in 3 out of 7 neuroblastoma cell lines examined, suggesting that MYT1L up-regulation may be a common event in both glioblastoma and neuroblastoma." (PMID 40362634, 2025). "Several studies suggested that MYT1L suppresses the proliferation of glioblastoma, and this transcript could have tumor-suppressive effects in HCCs as well." (PMID 35926060, 2022). "Taken together, these results suggest that in glioblastoma cells with normal DNA-PK activity, MYT1L may serve as an oncogene that contributes to the progression of glioblastoma by activating ERK1/2 and AKT signaling pathways, inhibiting apoptosis and shortening S phase in the cell cycle." (PMID 40362634, 2025). "It is interesting to look at the expression of DNA-PK, MYT1L, and CXCR1 and the levels of phosphorylated ERK1/2 in a large cohort of glioblastoma tissue samples and correlate the levels of these molecules to clinicopathological parameters of this disease." (PMID 40362634, 2025). "Next, we looked at the contributing role of MYT1L to an IL-8- and GROα-CXCR1 signaling loop in glioblastoma cells." (PMID 40362634, 2025). "The relationship between the MYT1L protein and CXCR1 mRNA levels was then examined in glioblastoma and neuroblastoma cell lines." (PMID 40362634, 2025).
glioblastoma (continued). "Furthermore, others have shown that MYT1L and MYT1 expression can slow tumor growth in glioblastoma cell line models via repression of pro-proliferative genes." (PMID 35869058, 2022).
glioma (4 papers, 2011 to 2025). A benign or malignant brain and spinal cord tumor that arises from glial cells (astrocytes, oligodendrocytes, ependymal cells). "Herein, we describe a selection of oncogenic (GLI-1/2/3, E2F1–8, STAT3, and HIF-1/2) and tumor suppressor (NFI-A/B, TBXT, MYT1, and MYT1L) TFs that are deregulated in gliomas and are subsequently associated with tumor development, progression, and migratory potential." (PMID 35409080, 2022). "Among the significant correlation changes in the network, we find three genes (MYT1L, EGFR, POSTN) known to have meaningful roles in glioma pathogenesis." (PMID 21756334, 2011).
epilepsy (3 papers, 2017 to 2024). A brain disorder characterized by episodes of abnormally increased neuronal discharge resulting in transient episodes of sensory or motor neurological dysfunction, or psychic dysfunction. "Out of the 14 patients carrying 22q13 deletions and having seizures, 4 were carrying an additional CNV covering a known risk gene for epilepsy: KCNT1 (OMIM: 608167), MYT1L (OMIM: 613084), DEAF1 (OMIM: 602635) and SLC25A22 (OMIM: 609302)." (PMID 29263841, 2017).
fibromyalgia (3 papers, 2015 to 2021). A chronic disorder of unknown etiology characterized by pain, stiffness, and tenderness in the muscles of neck, shoulders, back, hips, arms, and legs. "Polymorphism rs11127292 is located at the MYT1L (myelin transcription factor 1-like) gene and was associated with worse symptomatology in fibromyalgia patients." (PMID 30973927, 2019). "Rs11127292 in the MYT1L was found to be associated to fibromyalgia with low comorbidities." (PMID 26629533, 2015).
major depressive disorder (3 papers, 2010 to 2024). An episode of depression lasting two or more weeks without an intervening episode of mania. "It is worth noting that locus 17 (PPH4 = 82.04%, mapped gene: MYT1L) was also identified as one of the most important novel pleiotropic loci in the previous CPASSOC analysis of depression and HEM." (PMID 39588545, 2024). "MYT1L, CELF4 and MTCH2 were given priority as novel pleiotropic genes between depression and HEM." (PMID 39588545, 2024).
microcephaly (3 papers, 2016 to 2023). A congenital or acquired developmental disorder in which the circumference of the head is smaller than normal for the person's age and sex. "We believe this can explain how MYT1L loss can simultaneously lead to precocious neuronal differentiation in embryos (and thus later microcephaly), yet prolonged neuronal immaturity in adults." (PMID 37100461, 2023). "However, case 5 has borderline microcephaly, while the other individuals in the report of De Rocker et al18 who had similar deletions involving MYT1L but not SOX11 tended to have macrocephaly." (PMID 26543203, 2016).
22q11.2 deletion syndrome (2 papers, 2021 to 2025). 22q11.2 deletion syndrome (DS) is a chromosomal anomaly which causes a congenital malformation disorder whose common features include cardiac defects, palatal anomalies, facial dysmorphism, developmental delay and immune deficiency. "In total, 11/39 patients (28.2%) had a confirmed molecular diagnosis, including known IEIs such as Jacobsen syndrome, 22q11.2 deletion syndrome, and XLP2, as well as syndromes not yet officially recognized as IEIs (e.g., MYT1L, Down syndrome)." (PMID 41009569, 2025).
Anxiety (2 papers, 2022 to 2023). Intense feelings of nervousness, tension, or panic often arise in response to interpersonal stresses. "In humans, little is still known about the effects of MYT1L mutations on anxiety levels." (PMID 35538503, 2022). "We found that acute lamotrigine treatment in Myt1l-mutant mice normalised anxiety and hyperactivity behaviour in the open field test, as well as locomotion and rearing in home cage observations, towards untreated control mice." (PMID 36782060, 2023). "In the elevated plus maze, however, Myt1l haploinsufficiency led to reduced anxiety-related behavior and Myt1l+/- mice spent more time in the open arms than Myt1l+/+ littermates." (PMID 35538503, 2022). "Given the increased levels of locomotor activity together with the lower levels of anxiety-related behavior displayed by Myt1l heterozygous mice, however, it appears possible that this led to a reduction in freezing behavior." (PMID 35538503, 2022). "While the time spent in the center of the open field was not affected by Myt1l haploinsufficiency, the time spent in the open arms of the elevated plus maze was enhanced, reflecting reduced anxiety-related behavior." (PMID 35538503, 2022).
brain cancer (2 papers, 2022 to 2025). A primary or metastatic malignant neoplasm affecting the brain. "They further examined the relative expression levels of MYT1 and MYT1L in human brain cancer datasets showing that MYT1L was expressed in a lower rate in oligodendroglioma, astrocytoma (grade III), and GBM compared to normal brains." (PMID 35409080, 2022).
demyelinating disease (2 papers, 2023 to 2025). A broad group of disorders that affect the myelin sheaths that cover the neurons. "These biological functions position MYT1l as a promising therapeutic target for demyelinating diseases." (PMID 41210245, 2025). "The current study demonstrates the effective role of transcriptional regulators (OLIG2 and MYT1L) as a remarkable tool for stimulating myelin repair in lethal demyelinating disorders using cell-based therapeutic approach." (PMID 37232730, 2023).
malignant glioma (2 papers, 2019 to 2025). A grade III or grade IV glioma arising from the central nervous system. "Previously, we and others have reported that the combined transcription factors (BRN2/ASCL1/ MYT1L or NGN2/SOX11) could reprogram human malignant glioma cells into terminally differentiated neuron-like cells and successfully impede brain tumor development." (PMID 31212628, 2019).
melanoma (2 papers, 2022 to 2025). A malignant, usually aggressive tumor composed of atypical, neoplastic melanocytes. "For this purpose, we ectopically overexpressed the neuron-specific transcription factors ASCL1, BRN2, MYT1L, and NEUROD1 in melanoma cells." (PMID 40715046, 2025). "In order to examine if melanoma cells can be transdifferentiated into neurons, the neuron-specific transcription factors ASCL1, BRN2, MYT1L, and NEUROD1 were ectopically overexpressed in different melanoma cell lines." (PMID 40715046, 2025).
Allergy (1 paper, 2019). An allergy is an immune response or reaction to substances that are usually not harmful. "Meanwhile, the combination of Tranilast (an anti-allergy drug) with Temo upregulated master neuronal TFs such as MYT1L and NEUROD1." (PMID 30837577, 2019).
Alzheimer disease (1 paper, 2023). A progressive, neurodegenerative disease characterized by loss of function and death of nerve cells in several areas of the brain leading to loss of cognitive function such as memory and language. "Interestingly, MYT1L levels decrease during aging in both mice and humans, and loss of neuronal cell identity has recently been suggested to play a role in Alzheimer’s disease models, which suggests that neurodegeneration could also be regulated by the novel MYT1L-mediated mechanism presented here." (PMID 36782060, 2023).
Autosomal dominant intellectual disability type 39 (1 paper, 2025). "Autosomal dominant intellectual disability type 39 (MRD39; OMIM # 616521) is caused by heterozygous mutation in the MYT1l gene on chromosome 2p25.3." (PMID 41210245, 2025).
cardia (1 paper, 2013). "The contribution of MYT1L rs17039396 A allele to the improved survival of cardia gastric cancer patients were further evaluated by stratified analysis of tumor size, histological types, degree of differentiation, depth of invasion, lymph node metastasis, distant metastasis and TNM stage." (PMID 24015200, 2013).
cardia cancer (1 paper, 2013). A malignant neoplasm involving the cardia of stomach. "In the overall model, MYT1L rs17039396 polymorphism was associated with the survival of cardia cancer (log-rank P = 0.015)." (PMID 24015200, 2013). "Stratified analysis of MYT1L rs17039396 polymorphism among cardia cancer patients." (PMID 24015200, 2013). "In conclution, our results represent the first demonstration that MYT1L rs17039396 SNP may be associated with the prognosis of cardia cancer patients." (PMID 24015200, 2013). "Two variables (TNM stage and MYT1L rs17039396) were included in the regression model by stepwise selection of the covariant variables and rs17039396 SNP was shown to be an independent protective factor for cardia cancer with a 44% decreased risk (HR = 0.56, 95%CI = 0.39–0.79, P = 0.001)." (PMID 24015200, 2013). "We found that cardia cancer patients carrying MYT1L rs17039396 GG genotype survived for a significantly shorter time than those carrying the GA genotype." (PMID 24015200, 2013).
cognitive decline (1 paper, 2023). "MYT1L is a critical mediator of directly converting human brain vascular pericytes (HBVPs) into cholinergic neuronal cells, and the cholinergic deficit is thought to underlie progressed cognitive decline in AD." (PMID 37510227, 2023). "MYT1L gene, LRP1B gene and NEDD4L gene show strong associations with AD, and leading to cognitive decline in AD." (PMID 37510227, 2023).
gastric cancer (1 paper, 2013). A primary or metastatic malignant neoplasm involving the stomach. "In the present study, we genotyped 944 surgically resected gastric cancer patients by the SNaPshot method to explore the association of MYT1L rs17039396 polymorphism with survival of gastric cancer in a Chinese population." (PMID 24015200, 2013). "In conclusion, these data represents the first demonstration that MYT1L rs17039396 variants could indentified as a favorable prognostic indicator for gastric cancer, particularly among the cardia gastric cancer." (PMID 24015200, 2013). "Finally, for validation of the genotype–phenotype relationship, further investigation is underway to clarify the association between rs17039396 polymorphism and expression levels of MYT1L protein in gastric cancer tissues and will be reported separately." (PMID 24015200, 2013). "Association between MYT1L rs17039396 polymorphism and overall survival of gastric cancer." (PMID 24015200, 2013). "So we hypothesize that MYT1L gene may also be linked to gastric cancer." (PMID 24015200, 2013). "Consequently, testing for MYT1L rs17039396 SNP, combined with other traditional prognostic factors may significantly help distinguish a subgroup of patients with poor prognosis, thereby helping to refine therapeutic decisions in the treatment of gastric cancer." (PMID 24015200, 2013).
Huntington disease (1 paper, 2018). Huntington disease (HD) is a rare neurodegenerative disorder of the central nervous system characterized by unwanted choreatic movements, behavioral and psychiatric disturbances and dementia. "An enriched population of striatal MSN, the neuronal subtype primarily degenerated in Huntington’s disease (HD), can be derived using miR-9/9∗-124 in conjunction with CTIP2, DLX1/2, and MYT1L (CDM) factors." (PMID 30116172, 2018).
hypogonadotrophic hypogonadism (1 paper, 2017). "LEP and LEPR can be distinguished from MYT1L due to the association of hypogonadotrophic hypogonadism with LEP and LEPR SNVs." (PMID 28859103, 2017).
language delay (1 paper, 2022). "In their reports, many patients with MYT1L variants had language delay (95%), ID (70%), ASD (43%), motor delay (78%), and hypotonia (47%)." (PMID 35741772, 2022).
mental disorder (1 paper, 2010). A disease that has its basis in the disruption of mental process. "On the basis of a recent copy number variation (CNV) study showing that this gene is disrupted in mental disorder patients, we investigated whether MYT1L also plays a role in MDD." (PMID 21048971, 2010).
neuroblastoma (1 paper, 2025). Neuroblastoma (NB) is the most common solid, extracranial childhood tumor. "In neuroblastoma cell lines, CXCR1 was up-regulated in SH-SY5Y, SK-N-MC, and SK-N-SH lines, whereas only SH-SY5Y and SK-N-MC lines displayed a positive correlation between the MYT1L protein and CXCR1 mRNA levels." (PMID 40362634, 2025).
Neurodevelopmental delay (1 paper, 2023). "Additional phenotypes linked to ASD and MYT1L-associated NDDs include neurodevelopmental delays and changes in brain anatomy." (PMID 36782060, 2023).
POMC deficiency (1 paper, 2017). "Patients with POMC deficiency present with a range of endocrine problems not reported in association with MYT1L variants." (PMID 28859103, 2017).
spina bifida (1 paper, 2017). A congenital neural tube defect in which vertebrae are not fully formed. "The spina bifida in patient 4 is likely etiologically unrelated to the MYT1L SNV." (PMID 28859103, 2017).
thymic adenocarcinoma (1 paper, 2017).
neurodevelopmental disorder (11 papers, 2017 to 2025). A behavioral and cognitive disorder with onset during the developmental period that involves impaired or aberrant development of intellectual, motor, or social functions. "Human genetic research has demonstrated that mutations leading to the loss of function in Myt1l are associated with neurodevelopmental disorders." (PMID 39551613, 2025). "Mutations reducing the function of MYT1L, a neuron-specific transcription factor, are associated with a syndromic neurodevelopmental disorder." (PMID 39604385, 2024). "This duplication affects exons 3–19 of the MYT1L gene, which is associated with neurodevelopmental disorders." (PMID 38539661, 2024). "Recently, the gene Myelin Transcription Factor 1 Like (MYT1L) has been associated with neurodevelopmental disorders (NDD), with MYT1L loss of function now recognized as MYT1L Syndrome." (PMID 39764117, 2024). "Recently MYT1L has also been implicated in human neurodevelopmental disorders (NDDs), with the spectrum of symptoms caused by MYT1L loss of function (LoF) mutations now recognized as MYT1L Syndrome." (PMID 37100461, 2023). "Large scale human genetic studies have shown that loss of function (LoF) mutations in MYT1L are implicated in neurodevelopmental disorders (NDDs)." (PMID 35869058, 2022). "Haploinsufficiency for MYT1L has clear potential to disrupt expression of critical genes during brain development and hence cause a neurodevelopmental disorder." (PMID 28859103, 2017). "This suggests that MYT1L regulates a network of genes that control transcription, and which have themselves been implicated in the etiology of neurodevelopmental disorders." (PMID 28859103, 2017). "Mutations reducing the function of MYT1L, a neuron-specific transcription factor, are associated with a syndromic neurodevelopmental disorder, yet it remains unclear which cell types are most impacted by MYT1L loss." (PMID 39604385, 2024). "Through gene expression profiling of an MYT1L null cell line we show that MYT1L regulates a network of transcription factors involved in neurodevelopmental disorders." (PMID 28859103, 2017). "Also, we have identified 15 de novo variants in genes that were previously implicated in ASD or related neurodevelopmental disorders (PHF21A, WASF1, TCF20, DEAF1, MED13, CREBBP, KDM6B,SMURF1, ADNP, CACNA1G, MYT1L, KIF13B, GRIA2, CHM, and KCNK9)." (PMID 38572415, 2024). "In vitro studies indicate the neurodevelopmental disorder gene myelin transcription factor 1-like (MYT1L) suppresses non-neuronal lineage genes during fibroblast-to-neuron direct differentiation." (PMID 37100461, 2023). "MYT1L and RFX3 were also ranked as strong candidates specifically for ASD, rather than other neurodevelopmental disorders, according to the EAGLE score." (PMID 38409172, 2024).